FOXM1 (forkhead box M1)
Diseases named in the same sentence as FOXM1 in open-access papers (continued):
Sharing a sentence is not in itself a finding about the gene and the disease.
pulmonary fibrosis (continued). "Our findings suggest that ALKBH5 promotes silica-induced lung fibrosis via the miR-320a-3p/FOXM1 axis or targeting FOXM1 directly." (PMID 35279083, 2022). "Our work further confirmed that FOXM1 is the direct and functional target of miR-3p, and finally revealed the ALKBH5/miR-320q-3p/FOXM1 axis in lung fibroblasts activation during silica-induced lung fibrosis." (PMID 35279083, 2022). "And ALKBH5 promoted silica-induced lung fibrosis through miR-320a-3p/forkhead box protein M1 (FOXM1) pathway or targeting FOXM1 directly." (PMID 36494831, 2022). "Previous investigation showed that FOXM1 was more highly expressed in bleomycin-induced mouse lung fibrosis, and deletion of FOXM1 attenuated the pulmonary fibrosis." (PMID 35279083, 2022). "In general, these results showed the antifibrotic effect of miR-320a-3p in silica-induced pulmonary fibrosis by targeting FOXM1." (PMID 35279083, 2022). "The present findings suggest that ALKBH5 promotes silica-induced lung fibrosis via the miR-320a-3p/FOXM1 axis or by targeting FOXM1 directly in an m6A-dependent manner." (PMID 35279083, 2022). "ALKBH5 promotes silica-induced pulmonary fibrosis through miR-320a-3p/forkhead box protein M1 (FOXM1) axis or directly targeting FOXM1." (PMID 36553648, 2022). "Expression of FOXM1 in macrophages was examined in mouse lungs during progression of bleomycin-induced pulmonary fibrosis." (PMID 32271749, 2020). "To determine FOXM1 requirements in macrophages during progression of pulmonary fibrosis, we utilized a previously generated myeloid-specific Foxm1 knockout mouse model (LysM-Cretg/-;Foxm1fl/fl; abbreviated as myFoxm1-/-)." (PMID 32271749, 2020). "Mouse genetic studies demonstrated that deletion of Foxm1 from either AECII or fibroblasts inhibits pulmonary fibrosis." (PMID 32271749, 2020). "Using a translational approach, the authors showed that genetic deletion of FOXM1 in fibroblasts or pharmacological inhibition of FOXM1 inhibitor with Siomycin A attenuates BLM-induced pulmonary fibrosis." (PMID 32587955, 2020). "Following chronic bleomycin injury, deletion of Foxm1 increased the severity of pulmonary fibrosis as shown by H&E staining and Sircol assay measuring collagen content." (PMID 32271749, 2020). "Surprisingly, deletion of Foxm1 from myeloid cells exacerbated bleomycin-induced pulmonary fibrosis, indicating anti-fibrotic role of FOXM1 in myeloid lineage." (PMID 32271749, 2020). "Given a robust pro-fibrotic activity of FOXM1 in macrophage lineage and critical role of macrophages in mouse models of pulmonary fibrosis, the use of FOXM1 inhibitors in IPF or other fibrotic diseases should be approached with caution." (PMID 32271749, 2020). "In summary, macrophage-specific inactivation of FOXM1, exacerbates bleomycin-induced pulmonary fibrosis." (PMID 32271749, 2020). "Deletion of Foxm1 in myofibroblasts protected mice from bleomycin-induced pulmonary fibrosis and sensitized myofibroblasts to FasL-induced apoptosis." (PMID 32271749, 2020). "Previous studies have shown that Foxm1 increased radiation‐induced pulmonary fibrosis by promoting EMT in alveolar epithelial cells." (PMID 30378114, 2019). "A growing body of recent evidence has emphasized the potential roles of Foxm1 in organ fibrosis, such as pulmonary fibrosis and CF." (PMID 30378114, 2019). "Irradiated murine lung and human IPF fibrotic lesions both demonstrate increased FoxM1; the conditional deletion of FoxM1 prevented lung fibrosis in a murine model of radiation fibrosis." (PMID 29518028, 2018). "As FOXM1 accumulates in aged tissues, chemical or genetic abrogation of PGAM1-Chk1 binding impedes the protective role of FOXM1 in SnCs, inducing the death of senescent cells and alleviating dysfunction, including lung fibrosis, in vivo, indicating its potential efficacy as senotherapy." (PMID 41392167, 2025).
pulmonary fibrosis (continued). "Studie had discovered that ALKBH5 could regulate fibroblast-to-myofibroblast differentiation via the miR-320a-3p/FOXM1 axis or targeting FOXM1 directly, promoting silica-induced pulmonary fibrosis." (PMID 39220683, 2024). "Moreover, the deletion of FOXM1 in alveolar epithelial type II cells prevented lung fibrosis, while the overexpression of FOXM1 in these cells exacerbated fibrosis." (PMID 39944354, 2024). "The development of drugs targeting FOXM1 may be an effective strategy for preventing the progression of pulmonary fibrosis." (PMID 37238726, 2023). "FOXM1 plays an important role in the progression of radiation-induced lung fibrosis." (PMID 37238726, 2023). "This could explain, therefore, the anti-fibrotic role of FOXM1 in macrophages during pulmonary fibrosis." (PMID 37681924, 2023). "Moreover, decreased lung fibrosis was noted in the LPS + BMSCs-FoxM1 group relative to the LPS + BMSCs-Vector group." (PMID 36788588, 2023). "FOXM1 has an influential function in the development of pulmonary fibrosis." (PMID 37238726, 2023). "The current data suggest that single or combination therapy targeting FOXM1 may be effective in the treatment of diseases such as pulmonary fibrosis and inflammation." (PMID 37238726, 2023). "Furthermore, we verify the involvement of miR-320a-3p in the regulation of pulmonary fibrosis via targeting FOXM1, the latter of which we have previously validated to promote silica-induced pulmonary fibrosis." (PMID 35279083, 2022). "In the present study, we found a novel and unexpected role of FOXM1 in pulmonary fibrosis." (PMID 32271749, 2020). "Macrophage-specific deletion of Foxm1 in mice (myFoxm1-/-) exacerbated pulmonary fibrosis." (PMID 32271749, 2020). "Likewise, overexpression of FOXM1 in AECII exacerbated pulmonary fibrosis induced by thoracic irradiation or bleomycin, which is consistent with pro-fibrotic role of FOXM1." (PMID 32271749, 2020). "Altogether, FOXM1 expression in macrophages is critical to prevent pulmonary fibrosis." (PMID 32271749, 2020). "High levels of FOXM1 in type II epithelial cells and fibroblasts exacerbated pulmonary fibrosis." (PMID 32271749, 2020). "We next sought to determine whether FOXM1 correlates with the process of pulmonary fibrosis." (PMID 35279083, 2022). "Interestingly, we find that ALKBH5 can also target FOXM1 directly in pulmonary fibrosis." (PMID 35279083, 2022). "Thus, deletion of Foxm1 from myeloid cells increased lung fibrosis in bleomycin-treated mice." (PMID 32271749, 2020). "Consistently, thiostrepton, a FoxM1 inhibitor, exerted a mild senolytic effect on SnCs and significantly suppressed fibrotic areas and positive SA-β GAL staining in mouse lung fibrosis." (PMID 41392167, 2025). "In pulmonary fibrosis (PF) mice, HDAC3 combines with the profibrotic transcriptional factor forkhead box protein M1 (FOXM1) and binds to Nrf2 promoter, resulting in a decrease of local histone 3 acetylation and repression of Nrf2 and its transcription." (PMID 37072432, 2023). "In radiation-induced pulmonary fibrosis, the interaction of Foxm1 and Snail1 activates TGFβ1-induced EMT and promotes pulmonary fibrosis." (PMID 33639908, 2021). "Genetic deletion of Foxm1 in alveolar epithelial type II cells (AECII) prevented both radiation- and bleomycin-induced lung fibrosis in mice, while over-expression of FOXM1 in AECII exacerbated fibrosis." (PMID 32271749, 2020). "In fibrotic lung EMT, the forkhead box M1 (Foxm1) protein contributes to the EMT by transactivating the Snail1 gene under conditions of exposure to radiation, which induces lung fibrosis." (PMID 27367735, 2016). "Interestingly, prostaglandin E2, an endogenous inhibitor of FOXM1, drives AKT and FOXO3a phosphorylation through the modulation of the EP2/cAMP signaling pathway, thereby inhibiting the process of pulmonary fibrosis in mice." (PMID 37238726, 2023). "FOXM1 activates DUSP1 and inhibits the p38 MAPK signaling, therefore ameliorating lung fibrosis." (PMID 37569370, 2023).
pulmonary fibrosis (continued). "Notably, both FOXM1 and BIRC5 were found elevated in IPF-derived lung fibroblasts, and conditional deletion of Foxm1 in mouse fibroblasts accelerated lung fibrosis resolution following bleomycin challenge." (PMID 35167499, 2022). "Mice lacking Foxm1 in macrophages developed exacerbated pulmonary fibrosis following repeated intra-tracheal administration of bleomycin." (PMID 32271749, 2020). "Mice lacking FOXM1 in macrophages developed severe pulmonary fibrosis following repeated lung injury with bleomycin." (PMID 32271749, 2020). "However, in silica-induced pulmonary fibrosis, whether DDX3 is required for ALKBH5 to regulate the methylation status of miR-320a-3p and FOXM1 needs to be further investigated." (PMID 35279083, 2022). "In addition, inhibition of FOXM1 during the fibrotic phase was able to attenuate bleomycin-induced pulmonary fibrosis independent of widespread alveolar cell apoptosis." (PMID 30992007, 2019). "In the absence of FOXM1, the p38 MAPK pathway is activated in macrophages leading to production of pro-fibrotic mediators IL-1β, IL-6 and TNF-α that directly stimulate fibroblast activation and survival, exacerbating pulmonary fibrosis." (PMID 32271749, 2020).
breast tumor (35 papers, 2008 to 2026). "FOXM1 is overexpressed in breast tumors, including TNBC,124 and is strongly associated with tumor size, lymphovascular invasion, lymph node metastases, and advanced metastatic stages." (PMID 34981672, 2022). "The activation of cycling immune cells in breast tumors, as demonstrated by the subtype-independent high expression of FOXM1, may be associated with the advancement of carcinogenesis." (PMID 41584858, 2026). "Likewise, our immunohistochemistry (IHC) analysis of tumors from a cohort of 501 ERα-positive breast tumors revealed that high expression of FOXM1 protein was associated with a much poorer patient survival." (PMID 25213081, 2014). "In breast tumor cells, high expression of FoxM1 leads to the formation of a FOXM1/RB1 repression complex, which suppresses GATA3 and PTEN." (PMID 38672640, 2024). "Analysis of TCGA RNA sequencing data through the UALCAN platform revealed that the expression of ATAD2, E2F1, and FOXM1 were all significantly higher in primary breast tumor samples when compared to normal samples." (PMID 39335162, 2024). "Similar to this, it has been shown that FOXM1 overexpression confers the development of cisplatin resistance in breast tumor cells." (PMID 37626655, 2023). "We calculated the activity score of the FOXM1 pathway for TCGA breast tumors, including 424 luminal A, 121 luminal B, 37 HER2-enriched, 112 TNBC, and 112 normal breast tissue samples." (PMID 36424525, 2023). "To further understand the role of ER and FOXM1 linked topics identified in cell lines, we applied TITAN on a previously published patient breast tumor scRNA-seq dataset." (PMID 36318267, 2022). "A recent study demonstrated the promise of FOXM1 targeting compounds for suppressing breast tumors in preclinical models." (PMID 36318267, 2022). "Compared with its expression in normal breast tissue, FOXM1 has shown a different expression pattern in breast neoplasms." (PMID 36292640, 2022). "The correlation between elevated FOXM1 expression and endocrine resistance in breast tumors has previously been well-demonstrated." (PMID 33466512, 2021). "Here, we report on the FOXM1 inhibitory activity of these compounds in cell-free and cell-based assays, and in in vivo preclinical breast tumor models." (PMID 31815181, 2019). "It was found that, FoxM1 mRNA expression was significantly higher in breast tumor versus normal control." (PMID 29416660, 2018). "HOTAIR was shown to co-express with FOXA1 (forkhead box A1) and FOXM1 (forkhead box M1) in HER2-enriched breast tumors." (PMID 29469819, 2017). "We first compared the inferred regulatory activities of FOXM1 in ER-positive (ER+) versus ER-negative (ER−) breast tumor samples." (PMID 29100329, 2017). "Further, in large cohorts of patient breast tumors that we examined, high FOXM1 RNA and protein levels were found to correlate with a significantly faster onset of tumor recurrence and reduced overall survival." (PMID 25213081, 2014). "Consistent with FOXM1 overexpression in human breast tumours, malignant mammary cell lines such as MCF7, MDA-MB231, MDA-MB468, T47D and BT20 also exhibited increased FOXM1 levels when compared to benign mammary cell lines (HMEC, MCF10A and MCF12A)." (PMID 18254960, 2008). "Protein expression levels of cyclin-dependent kinase inhibitors, cyclins, ERs, FOXM1, and the proteins encoded by ER-regulated genes in MCF-7 cell lines and breast tumors were examined by immunoblotting analysis and immunohistochemical staining." (PMID 18312651, 2008).
breast tumor (continued). "In addition, using gene expression data from a large study with Tamoxifen-treated patients with ER-positive breast tumors, we showed that highly elevated FOXM1 mRNA correlated with reduced patient survival." (PMID 37370117, 2023). "In our current study, we report that depletion of Foxm1 in various cells that overexpress MAD2 (including human breast tumor cells, MEFs, normal mouse mammary epithelial cells and mouse tumor cells), leads to an extension of mitosis and an increase in mitotic errors." (PMID 37452072, 2023). "They speculated that the mechanisms leading to FOXM1 accumulation may contribute to palbociclib resistance in RB1-positive breast tumors." (PMID 37686402, 2023). "Further, because the level of FOXM1 generally increases as breast tumors progress, it suggests that the benefit from targeting FOXM1 might actually increase at later stages of the disease." (PMID 37370117, 2023). "Moreover, we also inferred the FOXM1 activities in breast tumor samples based on its target genes identified in the other six non-breast cell lines." (PMID 29100329, 2017). "Collectively, our findings demonstrate a positive regulatory feedback loop in which FoxM1 transactivates PDGF-A expression and the AKT signaling pathway, events that in turn elevate FoxM1 expression levels and promote breast tumor cell growth and tumorigenesis." (PMID 25869208, 2015). "We next analyzed the roles of FoxM1 in breast tumor cell growth in vitro." (PMID 25869208, 2015). "OGT may function as an oncogene, as it required for the survival of several breast tumor cell lines, and may regulate levels of p27Kip1 and FoxM1." (PMID 23029544, 2012). "Upregulation of FOXM1 mRNA in breast tumors could be confirmed on protein level when analysing the immunohistochemistry results from a tissue microarray." (PMID 18254960, 2008). "Interestingly, we found a positive correlation between FOXM1 expression and HER2 status, pointing to a potential role of FOXM1 as a new drug target in HER2 resistant breast tumour, as FOXM1 inhibitors for cancer treatment were described recently." (PMID 18254960, 2008). "Interestingly, we found a positive correlation between FOXM1 expression and HER2 status, additionally pointing to a potential role of FOXM1 as a new drug target in HER2 resistant breast tumour, as FOXM1 inhibitors for cancer treatment were recently described." (PMID 18254960, 2008). "The similarity of the FOXM1 pathway activity score in TCGA breast tumor tissue samples and GSE48213 BC cell lines suggests that the compounds that can modulate the FOXM1 pathway in BC cell lines could also potentially modulate the pathway in breast tumor tissue samples." (PMID 36424525, 2023). "Interestingly, we could find a positive correlation between FOXM1 expression and HER2 status pointing to the potential role of FOXM1 as a new drug target in HER2 resistant breast tumour." (PMID 18254960, 2008). "We harvested breast tumor cells from TetO-Kras/MMTV-rtTA transgenic mice (K) and TetO-Kras/TetO-Mad2/MMTV-rtTA mice (KM) and observed higher Foxm1 mRNA and protein levels in KM compared to K tumor cells." (PMID 37452072, 2023). "The up-regulation of FOXM1 together with XIAP and Survivin antiapoptotic genes induces resistance in breast tumor cells to docetaxel, paclitaxel, and epirubicin." (PMID 36424525, 2023). "The high difference in DEPDC1, NUSAP1, FOXM1 and MUC1 gene expression observed between metastatic tissues and primary breast tumours can be considered as a prognostic marker for the development of metastases." (PMID 37958607, 2023). "With the BC cell lines, we were surprised to see that the distribution of the FOXM1 and PPARA pathway activity scores in breast tumor cell lines is similar to that in TCGA breast tumor patients." (PMID 36424525, 2023).
breast tumor (continued). "This study also revealed that MMP1, VCAM1, FZD3, VEGFC, FOXM1 and MUC1 genes can be considered as markers of breast cancer occurrence because these genes show significant differential expression in breast neoplasms compared to normal tissue." (PMID 37958607, 2023). "In conclusion, we have shown that FOXM1 expression is a biomarker of response and resistance to PI3Kα inhibition in ER+PIK3CA-mutant breast tumors." (PMID 32976773, 2020). "Our results provide further evidence on molecular signals governing breast tumor angiogenesis under the coordinate control of the two master regulators of tumorigenesis HMGA1 and FOXM1." (PMID 31311575, 2019). "Our results demonstrate that HMGA1 cooperates with FOXM1 in regulating the expression of a common gene network, enhancing the aggressiveness of TNBC cells, highlighting a dependence of breast tumor cells on HMGA1 and FOXM1 synergic action." (PMID 31311575, 2019). "Moreover, we compared FOXO3a, FOXM1, SOX2, and DNMT1 expression in a tissue microarray containing 100 independent primary breast tumor samples and 32 adjacent normal breast tissues by immunohistochemistry." (PMID 31296961, 2020). "As FOXM1 is an important regulator of the mitogenic functions of ERα in breast tumor cells, we hypothesized that RASSF1A may exert some of its suppressive effects on ERα through regulating FOXM1 expression and activity." (PMID 32967092, 2020). "This regulatory feedback loop between FoxM1 and PDGF/AKT maintains the consecutive activation of the AKT signaling pathway, which may be a critical mechanism for breast tumor progression." (PMID 25869208, 2015). "In primary and metastatic cancers, FOXM1 contributes to invasion, epithelial-mesenchymal transition (EMT) and metastasis through up-regulation of matrix metalloproteinase (MMP)-2, c-Met, pAKT, vimentin, and modulation of E-cadherin and related factors in breast tumors." (PMID 37370117, 2023). "However, this study neither analysed FOXM1 protein expression in breast tumour tissues nor did it evaluate the impact of FOXM1 deregulation on patient prognosis." (PMID 18254960, 2008).